STAT3 (signal transducer and activator of transcription 3)
Diseases named in the same sentence as STAT3 in open-access papers (continued):
Sharing a sentence is not in itself a finding about the gene and the disease.
breast cancer (continued). "In addition, the approach through which IL6/STAT3 regulates breast cancer development is thought to be by promoting Jak and angiogenesis signaling, which has been documented recently." (PMID 34833950, 2021). "Indeed, the administration of alisertib ameliorated immunosuppressive function of MDSCs by inhibiting STAT3-mediated ROS generation in breast cancer." (PMID 33957948, 2021). "Finally, we show that TrkA interacts directly with and phosphorylates STAT3 on Y705 to promote oncogenic gene transcription, implicating a novel mechanism to activate STAT3-mediated breast cancer metastasis in TrkA-overexpressing tumors." (PMID 34066153, 2021). "Notably, STAT3 knockdown or upstream inhibition through the JAK1/2 kinase inhibitor ruxolitinib prevented opioid-induced breast cancer cell metastasis and migration in vitro and in vivo." (PMID 33465556, 2021). "Moreover, tumor-infiltrating NKs and MDSCs underwent transcriptional reprogramming and enhanced the IL-10 production via STAT3 in breast cancer." (PMID 33957948, 2021). "Similarly, activation of the STAT3/NFκB pathway in breast cancer cells by M1 macrophage secreted pro-inflammatory cytokines elicits Lin28B-let-7-HMGA2 axis to induce CD44+/CD24- and ALDH1+ CSCs through activation of EMT." (PMID 34572067, 2021). "The overexpression of STAT3 could reverse miR-365a-3p or circNOLC1 depletion-inhibited proliferation and cancer stem cell properties of breast cancer." (PMID 34789263, 2021). "Three genes CCND1, ESR1, and STAT3 were enriched for mammary neoplasms, experimental (C0024668)." (PMID 34504716, 2021). "Several STAT3 inhibitors have also entered clinical trials for obesity-linked cancers, including pancreatic cancer (phase III), metastatic colorectal cancer (phase II), ovarian cancer (phase II), hepatocellular carcinoma (phase I), and breast cancer (phase I)." (PMID 34156978, 2021). "In this review, the only study found linking this miRNA to some light-involving therapeutic tool regarded breast cancer, but it can be suggested to extend this treatment to other skin tumors where the pathway of STAT3 could be of pathogenetic significance." (PMID 34439557, 2021). "Meanwhile, miR-365a-3p mimic reduced the SP ratio in MDA-MB-231 and MDA-MB-468 cells, while the STAT3 overexpression reversed the inhibition, implying that the overexpression of STAT3 rescues miR-365a-3p-inhibited proliferation and cancer stem cell activity of breast cancer." (PMID 34789263, 2021). "Conversely, SOX2 or MYC mRNAs were significantly downregulated in cells expressing TrkA-K538N, nearly to the levels found in the vector controls, suggesting that TrkA kinase activity is essential for inducing STAT3 target gene transcription in breast cancer cells." (PMID 34066153, 2021). "High-expression of Anxa2 could directly regulate STAT3 and consequently enhance the invasion and metastasis in breast cancer cells." (PMID 33903672, 2021). "Additional research revealed that breast cancer stem cells stemness characteristics could be lost by JAK2/STAT3 signaling pathway blockage." (PMID 34900727, 2021). "Therefore, we used sotrastaurin to block PKC to reduce the NF-κB/STAT3 signaling pathway and investigated mechanisms in breast cancer cells." (PMID 34381775, 2021). "Hence, the inhibition of Jak/STAT3 signaling mitigates the breast cancer stem cells’ identity and the expression of various lipid metabolic genes." (PMID 34833950, 2021). "Thus, the employment of STAT3 inhibitors in combination with PD-L1 blockers can be a useful alternative for breast cancer patients with overexpression of STAT3." (PMID 33506060, 2021). "Importantly, IL-6 activates STAT3—as we found in our experiments—giving the IL-6/JAK/STAT3 pathway a key role in tumour progression in a variety of types, including breast cancer." (PMID 34948097, 2021).
breast cancer (continued). "Interestingly, autophagy induced by the activation of Src/STAT3/HO-1 was found to protect several subtypes of breast cancer cells from doxorubicin-induced cytotoxicity." (PMID 33801351, 2021). "Indeed, apart from its oncogenic role in tumor cells, the functions of STAT3 in TME of breast cancer involve multiple types of immunosuppression and is associated with tumor cell metastasis." (PMID 33957948, 2021). "Besides, study on activity of metformin against breast cancer cell lines showed that metformin significantly reduced both tyrosine and serine phosphorylation of STAT-3 (P-STAT-3 at Tyr705 or Ser727), reduced P-mTOR and induced P-AMPK/AMPK." (PMID 34535145, 2021). "The EGFR and Src-mediated STAT3 signalling pathway is activated in TamR cells, and inhibition of STAT3 may be a potential target in tamoxifen-resistant breast cancer." (PMID 34407787, 2021). "Apparently, EZH2 reciprocally bound to STAT3 in breast cancer cells." (PMID 34335938, 2021). "Furthermore, studies have suggested that SPHK1/S1P/S1PR1 signaling pathway also aids to mediate treatment-induced inflammation and resistance to doxorubicin and tamoxifen in breast cancer, which is also accompanying with upregulation of NF-κB/IL-6/STAT3." (PMID 34820423, 2021). "The STAT3-PKCε reciprocal immunoprecipitation has indicated this molecular interaction in skin melanomas, prostate, gliomas, bladder, colon, lung, pancreatic, and breast cancer cells." (PMID 34440160, 2021). "Chemical and genetic inhibition of EZH2 impeded proliferation and migration of breast cancer cells, which may be partially rescued by STAT3 over-expression." (PMID 34335938, 2021). "Thus, TrkA-mediated activation of STAT3 can induce the expression of stemness genes to support breast cancer progression." (PMID 34066153, 2021). "In addition, an antidiarrheal agent (nifuroxazide) was also identified as a potent inhibitor of STAT3, which markedly inhibited the phosphorylated-Stat3Tyr705 in breast cancer, and induced cancer cell apoptosis in a dose-dependent manner." (PMID 33957948, 2021). "A previous finding has shown that exosomes secreted by breast cancer cells can skew macrophage polarization toward a pro-tumoral M2-like phenotype partially via gp130/STAT3 signaling, suggesting that the tumor-derived exosomes mediate immune-suppressive activity of macrophages." (PMID 34650968, 2021). "Although MRE11-dependent transformation in breast cancer was linked to signal transducer and activator of transcription 3 (STAT3) signaling, no such association was found in oral cancer." (PMID 34638302, 2021). "A recent study found that miR-93-5p could target STAT3 to inhibit epithelial-mesenchymal transition in breast cancer." (PMID 33535997, 2021). "Similarly, S3I-201 has been reported to suppress the radiation-induced STAT3 phosphorylation and increase the radiation-induced cell death in breast cancer." (PMID 33957948, 2021). "Moreover, baicalein showed anti-metastatic activity in breast cancer in vitro and in vivo demonstrated by the inhibition of STAT3 activity and suppressed IL-6." (PMID 34950252, 2021). "Accumulating evidence suggests that targeting STAT3 and/or in combination with radiotherapy may enhance anti-cancer immune responses and rescue the systemic immunologic microenvironment in breast cancer." (PMID 33957948, 2021). "Besides the MAPK pathway, the STAT3 (signal transducer and activator of transcription 3)-pathway plays an important role in progression and metastasis of breast cancer by promoting angiogenesis and is increasingly phosphorylated in ca. 40% of breast cancers." (PMID 34185141, 2021). "Moreover, another low-molecular compound STA-21 has also been identified as a selective STAT3 inhibitor that influences the STAT3 dimerization and DNA binding ability in breast cancer." (PMID 33957948, 2021).
breast cancer (continued). "Alshaker and colleagues demonstrated that leptin as an adipokine was able to induce upregulation of SPHK1 and in turn SPHK1 could contribute to leptin-induced STAT3 activity in breast cancer via transactivation of IL-6/gp130." (PMID 34820423, 2021). "Our data suggest that inhibition of STAT3 may be a treatment option for patients with endocrine-resistant breast cancer through Src/EGFR/STAT3 activation." (PMID 34407787, 2021). "STAT3 is aberrantly activated in approximately 70% of breast cancer patients." (PMID 34120621, 2021). "PTPN9 may contribute to tumor suppression by dephosphorylation and silencing of EGFR, ErbB2, and STAT3 in breast cancer." (PMID 34199293, 2021). "In addition, previous reports have shown that PD-L1 expression is regulated through the STAT3 or NF-κB signaling pathway in various cancer cells, such as non-small lung cancer, melanoma, and breast cancer." (PMID 34885221, 2021). "In the current study, we demonstrate that BQ overexpression could enhance the expression of IL-6 and IL-6R, which in turn activates the IL-6/STAT3 pathway to mediate tamoxifen resistance in breast cancer." (PMID 33806019, 2021). "In our study, we confirmed that overexpression of BQ could lead to the activation of IL-6/STAT3 pathway, which conferred resistance to tamoxifen in ER+ breast cancer cells." (PMID 33806019, 2021). "Candidate pathways were constructed starting from the estrogen receptor ESR1 gene and targeting breast cancer-associated transcription factors, such as JUN, FOS, STAT1, STAT3, STAT5A, ELK1, and ETS1 (Target transcription factors were pre-identified by GibbsOS19)." (PMID 33432018, 2021). "Many cytokine and growth factor receptors trigger JAK1/2-STAT3/5 activation, however, it was somewhat unexpected and striking that a GPCR such as DOR could also activate STAT3 in breast cancer cells to a similar extent as IL-6 cytokine stimulation." (PMID 33465556, 2021). "Herein, we discuss the STAT3 related T cells immunosuppression in breast cancer as follows." (PMID 33957948, 2021). "It has also been shown that JAK1 plays an important role in STAT3 activation in breast cancer." (PMID 34066153, 2021). "In addition, STAT3 plays a critical role in breast cancer chemoresistance and stem cell self-renewal." (PMID 33823894, 2021). "Consistently, IL-6 is known to play a crucial role in STAT3 activation in breast cancer." (PMID 34833950, 2021). "Interestingly, the STAT3/Cyclin D1 axis is activated in several cancer types including breast cancer." (PMID 35003089, 2021). "Notably, we utilized pharmacologic inhibition of JAK1/2 and stable genetic STAT3 knockdown to conclude that opioid-triggered STAT3 activation promotes breast cancer migration and metastasis." (PMID 33465556, 2021). "Though TCGA data mining showed that STAT3 mRNA was not altered between normal cohorts and patients, survival and protein analysis showed that STAT3 was associated with breast cancer." (PMID 34335938, 2021). "Importantly, in tissues such as the endometrium and breast cancer cells, STAT3 has been shown to specifically bind to PR-A, and co-activate its transcriptional functions." (PMID 34566984, 2021). "miR-155 induces HK2 by transcriptional activation by the signal transducer and activator of transcription 3 (STAT3) as a transcriptional activator or post-transcriptional regulation via repression of miR-143a as a negative regulator of HK2 in human breast cancer cells." (PMID 33922649, 2021). "Recently, GREM1 was reported to activate STAT3 signaling in breast cancer cells." (PMID 33967807, 2021). "In this study, we firstly identified that circRHOT1 could inhibit ferroptosis and promote the progression of breast cancer by modulating the miR-106a-5p/STAT3 axis." (PMID 33686957, 2021).
breast cancer (continued). "STAT3 is involved in the regulation of hypoxia-stimulated chemoresistance in breast cancer." (PMID 35004266, 2021). "Furthermore, we expanded our investigation of TrkA and STAT3 co-activation by performing a Western blot analysis using breast cancer cell lines of varying subtypes." (PMID 34066153, 2021). "In particular, constitutive activation of STAT3 has been shown to play an essential role not only in acute myeloid leukemia, Hodgkin lymphoma, nasal-type natural killer cell lymphoma but also gastric cancer, ovarian cancer and breast cancer." (PMID 32270320, 2021). "We and others have previously reported that K685 acetylation is elevated in breast cancer, colon cancer, and melanoma, and the acetylation of STAT3 is critical for its dimerization and activation, strongly supporting the concept that acetylated STAT3 is a viable therapeutic target." (PMID 33491667, 2021). "Similarly, the activation of STAT3 seems to be correlated with the relapse of patients after radiotherapy in breast cancer." (PMID 34141616, 2021). "Therefore, STAT3 methylation by EZH2 was critical for the nuclear localization in breast cancer cells." (PMID 34335938, 2021). "Interestingly, opioid-exposed breast cancer cells showed enhanced migration and strong STAT3 activation, which was efficiently blocked by a DOR-antagonist." (PMID 33465556, 2021). "However, the correlation of circRHOT1 with miR-106a-5p and STAT3 in the development of breast cancer is still elusive." (PMID 33686957, 2021). "Previous research showed that angiogenesis and tumor growth of breast cancer cells could be attenuated by inhibiting STAT3-VEGF expression both in vitro and in vivo in an acidic tumor environment." (PMID 33632325, 2021). "EZH2 promotes proliferation and migration of breast cancer cells by methylating STAT3." (PMID 34335938, 2021). "Interestingly, miR-210 expression is correlated with metastasis of breast and melanoma tumors under the control of STAT3 in mammary carcinoma." (PMID 34299605, 2021). "STAT3 is a known breast oncogene that may bestow a direct survival advantage on breast cancer cells in addition to modulating the tumour microenvironment to facilitate neoplastic cell survival and/or infiltration and invasion." (PMID 33280071, 2021). "Excessive activation of signal transducer and activator of transcription 3 (STAT3) is implicated in breast cancer (BC) chemoresistance, but its underlying mechanism is not fully understood." (PMID 34076564, 2021). "Interestingly, synergistic pathway cross-talk most likely exists between the STAT3 and PPARA as they converge on upregulation of nuclear expression of CPT1 driving FAO as an energy source in breast cancer-adipose associations." (PMID 32331320, 2020). "Furthermore, in human breast cancer tissues, elevated G-CSF expression in adipocytes is well correlated with activated Stat3 signal in cancer cells." (PMID 32242230, 2020). "NF-kB and STAT3 form a network to mediate inflammatory in breast cancer cells." (PMID 32190078, 2020). "Furthermore, the IL-6/JAK/STAT3 pathway has been shown to be important for the proliferation of CD44+CD24− stem cell–like breast cancer cells." (PMID 32328465, 2020). "Interestingly, glutamine was shown to activate STAT3 to induce cell growth and proliferation in breast cancer cells, indicative of an interplay/feedback loop between metabolic pathways and STAT3 activation." (PMID 33266219, 2020). "We showed that serotonin, through 5-HTR2A/C, interferes with breast cancer cells proliferation and metabolism by triggering two distinct signalling pathways: Jak1/STAT3 that boosts glycolysis through upregulation of PKM2, and adenylyl cyclase/PKA that enhances mitochondrial biogenesis." (PMID 31819176, 2020).
breast cancer (continued). "The effect of hnRNPA2B1 on the occurrence and development of breast cancer may be through the role of STAT3 and ERK1/2-related signaling pathways." (PMID 32463472, 2020). "Furthermore, the activation of JAK2/STAT3 favors proliferation and motility of breast cancer cells by different mechanisms, including the suppression of apoptosis by upregulation of cyclin D-1, c-Myc, and Bcl-2, and promotion of EMT." (PMID 33138097, 2020). "It seems that STAT3 is a target of miR-93 in breast cancer cells." (PMID 32612456, 2020). "Especially for breast cancer patients suffering from doxorubicin or capecitabine resistance, STAT3 inhibitors instead of expensive monoclonal antibodies may be more beneficial." (PMID 32111215, 2020). "This point might expand the application of STAT3 inhibitors in the clinical treatment of ERα‐positive breast cancer patients." (PMID 33173749, 2020). "Further experiments on HCC1143 cells demonstrated that EGF-mediated increases in MAPK activation reduced basal STAT3 activation in a MEK dependent manner, strengthening the connection between MAPK signaling and STAT3 activation in human breast cancer cell lines." (PMID 33062958, 2020). "In addition, STAT3 expression was analyzed in 139 cases of human breast cancer including 117 cases of non-triple negative breast cancer (non-TNBC) (group I) and 22 cases of triple-negative breast cancer (TNBC) (group II)." (PMID 32432040, 2020). "In support of this hypothesis, it was found that tumor-residing macrophages can induce Sox2 expression in murine breast cancer cells in a STAT3-depending manner and thereby increase CSC activity." (PMID 33228022, 2020). "Breast cancer with bone metastasis shows significantly increased expression of IL-11 in comparison with breast cancer without bone metastasis, and IL-11 is known to be involved in bone metastasis through the gp130/STAT3 pathway." (PMID 32674405, 2020). "In addition, Stattic treatment abolished rhG-CSF-mediated upregulation of mesenchymal markers at both protein and mRNA levels, indicating that G-CSF/Stat3 signaling is able to promote EMT of breast cancer cells." (PMID 32242230, 2020). "For the first time, we show that PAA can selectively block breast CSCs formation through ROS induction/Stat3 dephosphorylation, mediated blockade of Stat3 signal pathway in breast cancer-derived mammosphere cells, and PAA is effective inhibiting tumor growth using the mouse xenograft model." (PMID 33202749, 2020). "Furthermore, the interference of STAT3 (the transfection of si-STAT3) in linc00514-OVE breast cancer cells elevated the mRNA levels of TNF-α, NOS2, and IL-6, and reduced the expression of Arg-1 at both mRNA and protein levels." (PMID 32943090, 2020). "In a breast cancer cell line, filgotinib inhibited STAT3 phosphorylation; in combination with a histone deacetylase inhibitor, there was increased apoptosis in breast cancer cells as well as tumor growth inhibition in mice harboring breast cancer tumors." (PMID 33521321, 2020). "In human breast cancer, morusin induced apoptosis by decreasing Survivin and increasing Bax protein expression and induces apoptosis through inhibiting signal transducer and activator of transcription 3 (STAT3) in the prostate cancer." (PMID 33096744, 2020). "Furthermore, the silencing of B7-H3 increased the sensitivity of multiple human breast cancer cell lines to paclitaxel by abrogating Jak2/Stat3 phosphorylation." (PMID 32127943, 2020). "Mechanistically, arctigenin decreased the promoter activities of GM-CSF and TSLP via hindering the nuclear translocation of NF-κB p65, and consequently, inhibited STAT3/β-catenin signaling, resulting in decreased proliferation, invasion and stemness of breast cancer cells in vitro and in vivo." (PMID 32887217, 2020).